ANKRD28 (ankyrin repeat domain 28)
Description:
Regulatory subunit of protein phosphatase 6 (PP6) that may be involved in the recognition of phosphoprotein substrates. Involved in the PP6-mediated dephosphorylation of NFKBIE opposing its degradation in response to TNF. Selectively inhibits the phosphatase activity of PPP1C. Targets PPP1C to modulate HNRPK phosphorylation. Involved in the PP6-mediated dephosphorylation of MOB1 and induced focal adhesion assembly during cell migration.
Synonyms: PP6-ARS-A; PITK; KIAA0379; PPP1R65; FAP79; CFAP79
Tractability: PROTAC: UniProt records ubiquitination sites on it; ubiquitination databases record sites on it; its protein half-life has been measured.
Target class: Protein phosphatase regulatory subunit; Phosphatase; Enzyme; Protein Phosphatase
Gene: Protein-coding gene on chromosome 3 (15,667,236 to 15,859,771, reverse strand). Ensembl gene ENSG00000206560.
Subcellular location: Nucleus, nucleoplasm; Cytoplasm, cytosol; Cell projection, lamellipodium
Pathways (Reactome):
Cell Cycle: Telomere Extension By Telomerase
Vesicle-mediated transport: COPII-mediated vesicle transport
Gene Ontology:
Molecular function: protein binding; protein phosphatase regulator activity
Biological process: positive regulation of focal adhesion assembly
Cellular component: cytosol; lamellipodium; protein serine/threonine phosphatase complex; nucleoplasm
Genetic constraint (gnomAD): Loss-of-function variants: 29 observed, 86.91 expected, observed/expected ratio (o/e) 0.33, 90% interval 0.25 to 0.46. The upper end of that interval is the gene's LOEUF score, 0.46, which puts it in group 2 of 6, group 1 being the genes least tolerant of losing a copy. Missense variants: 935 observed, 1,100.3 expected, observed/expected ratio (o/e) 0.85, 90% interval 0.81 to 0.9. Synonymous variants: 373 observed, 396.17 expected, observed/expected ratio (o/e) 0.94, 90% interval 0.86 to 1.03.
Homologues: Orthologues: macaque ANKRD28 (99% identical), dog ANKRD28 (99% identical), pig ANKRD28 (99% identical), rabbit ANKRD28 (98% identical), chimpanzee ANKRD28 (98% identical), guinea pig ANKRD28 (97% identical), rat Ankrd28 (95% identical), mouse Ankrd28 (95% identical), tropical clawed frog ankrd28 (90% identical), zebrafish ankrd28b (84% identical). Paralogues in human: ANKRD44 (63% identical), ANKRD52 (58% identical), ANKRD55 (15% identical).
Diseases named in the same sentence as ANKRD28 in open-access papers:
ANKRD28 is named in the same sentence as 9 diseases in open-access papers, as found by Europe PMC text mining. Sharing a sentence is not in itself a finding about the gene and the disease. The quoted sentences say what the papers report.
acute myeloid leukemia (2 papers, 2021 to 2025). Acute myeloid leukemia (AML) is a group of neoplasms arising from precursor cells committed to the myeloid cell-line differentiation. "In addition, ANKRD28 has been confirmed as an oncogene in acute myeloid leukemia." (PMID 33663517, 2021).
breast cancer (2 papers, 2022 to 2025). A primary or metastatic malignant neoplasm involving the breast. "Importantly, ANKRD28-containing PP6 complex inhibits FA formation, and Rab40c directly regulates ubiquitination and degradation of ANKRD28 in breast cancer cells." (PMID 35512830, 2022). "Here, we show that Rab40c regulates the size, location, and number of FAs in breast cancer cells, while also demonstrating that Rab40c interacts with ankyrin repeat domain 28 protein (ANKRD28), which is a scaffolding subunit of heterotrimeric protein phosphatase PP6 complex." (PMID 35512830, 2022). "For instance, it showed target pairing between piR-823 and lncRNA for the BRAC1 gene in breast cancer (BC), SH3BP2 in renal cell carcinoma (RCC), and ANKRD28 in hepatocellular carcinoma (HCC)." (PMID 39102033, 2025).
dwarfism (2 papers, 2022 to 2024). "We propose the heterozygous c.2dupT variant as a candidate causative variant for the observed congenital disorder and ANKRD28 as a novel candidate gene for dwarfism phenotypes." (PMID 35451514, 2022). "Further individual cases of dwarfism in cattle or other animal species could be investigated for ANKRD28 variants by DNA sequencing." (PMID 35451514, 2022).
COVID-19 (1 paper, 2025). A disease caused by infection with severe acute respiratory syndrome coronavirus 2. "PLWH with COVID-19 had significantly lower plasma ANKRD28 levels than HC but similar levels to PLWH without COVID-19." (PMID 40568587, 2025).
cancer (3 papers, 2021 to 2022). A tumor composed of atypical neoplastic, often pleomorphic cells that invade other tissues. "While the ANKRD28 gene has an unknown role in GB, the tyrosine phosphatase PTPRD is a tumor suppressor that is frequently inactivated and mutated in GB and other human cancers." (PMID 36132155, 2022). "Thus, although additional studies will be needed to determine the mechanisms of PP6-dependent FAK regulation, our data imply that the Rab40c-ANKRD28/PP6 pathway contributes to regulating FAK activity and FA disassembly during cancer cell migration." (PMID 35512830, 2022).
tumor (1 paper, 2022). "Non-responsive tumor portions had consistently complete loss of ANKRD28 and PTPRD expression unlike their responsive counterparts." (PMID 36132155, 2022).
ANKRD28 also shares sentences with these, for which no sentence is quoted: hematologic neoplasms (1 paper); hepatocellular carcinoma (1); renal cell carcinoma (1).